CIMIP4 (ciliary microtubule inner protein 4)
Description:
Seems to be associated with spermiogenesis but is not essential for sperm development and male fertility.
Synonyms: C22orf33; EAN57; TEX33; MGC35206; cE81G9.2
Tractability: No criterion of Open Targets' tractability assessment is met for any kind of drug.
Gene: Protein-coding gene on chromosome 22 (36,991,120 to 37,007,851, reverse strand). Ensembl gene ENSG00000185264.
Subcellular location: Cytoplasmic vesicle, secretory vesicle, acrosome; Cell projection, cilium, flagellum
Gene Ontology:
Cellular component: sperm flagellum; acrosomal vesicle; motile cilium
Genetic constraint (gnomAD): Loss-of-function variants: 27 observed, 30.7 expected, observed/expected ratio (o/e) 0.88, 90% interval 0.65 to 1.21. The upper end of that interval is the gene's LOEUF score, 1.21, which puts it in group 5 of 6, group 1 being the genes least tolerant of losing a copy. Missense variants: 373 observed, 346.41 expected, observed/expected ratio (o/e) 1.08, 90% interval 0.99 to 1.17. Synonymous variants: 158 observed, 138.93 expected, observed/expected ratio (o/e) 1.14, 90% interval 1 to 1.3.
Homologues: Orthologues: chimpanzee CIMIP4 (99% identical), macaque CIMIP4 (91% identical), dog CIMIP4 (71% identical), pig CIMIP4 (65% identical), rabbit CIMIP4 (63% identical), mouse Cimip4 (62% identical), rat Cimip4 (61% identical), guinea pig CIMIP4 (57% identical), tropical clawed frog tex33 (23% identical).
Diseases named in the same sentence as CIMIP4 in open-access papers:
CIMIP4 is named in the same sentence as 2 diseases in open-access papers, as found by Europe PMC text mining. Sharing a sentence is not in itself a finding about the gene and the disease.
CIMIP4 shares sentences with these, for which no sentence is quoted: cancer (1 paper); chronic myeloid leukemia (1).